CXCL10 (C-X-C motif chemokine ligand 10)
Diseases named in the same sentence as CXCL10 in open-access papers (continued):
Sharing a sentence is not in itself a finding about the gene and the disease.
tumor (continued). "Meanwhile, the increased expression of CXCL10 may result from the upregulation of upstream anti-tumor immune responses, thereby promoting the infiltration of T cells and NK cells and triggering immune responses." (PMID 40805064, 2025). "In the PRMT5-knockdown alone model, PRMT5 knockdown tumor cells secrete high levels of CXCL10." (PMID 41463372, 2025). "In addition, the association of CXCL10 and CCL4 levels with the densities of all T cell subtypes increased when the tumor cell nests were specifically analyzed." (PMID 40497965, 2025). "CXCL10 is a chemoattractant for activated T cells and may enhance the homing of T cells to the tumor site(s)." (PMID 40243928, 2025). "‎Personalized gene ‎therapy strategies that ‎adjust CXCL10 expression based on the molecular profile of ‎the individual ‎tumor offer the ‎potential for highly targeted and effective cancer treatments that ‎maximize the ‎immune ‎system’s ability to combat cancer." (PMID 40760734, 2025). "Co-culture studies of OS cell lines with THP1-derived M0 or M2 macrophages revealed marked CXCL10 upregulation compared with monocultures, suggesting that CXCL10 contributes to macrophage polarization toward a tumor-promoting M2 phenotype and helps sustain their immunosuppressive activity." (PMID 41516196, 2025). "Notably, CAR-M post-tumor stimulation exhibited elevated secretion of T/NK cell-recruiting chemokines (Cx3cl1, Ccl5, Cxcl10), with Cxcl10 secretion further validated by ELISA." (PMID 41388305, 2025). "Conversely, DNMT1-mediated methylation silences chemokines such as CXCL9 and CXCL10, leading to reduced anti-tumor immune cell infiltration; the restoration of TET1 and TET2 can reverse this effect and improve the efficacy of immune checkpoint inhibitors (ICIs)." (PMID 41394878, 2025). "Moreover, we used an ELISA kit to detect the secretion of CXCL9 and CXCL10 in the subcutaneous and orthotopic tumor models." (PMID 40008893, 2025). "For example, the chemokine CXCL10 promotes the infiltration of T cells into the tumor microenvironment, enhancing anti-tumor immunity, while CCL20 recruits Tregs via the FOXO1/CEBPB/NF-κB signaling pathway, thereby promoting chemotherapy resistance in colorectal cancer." (PMID 41200171, 2025). "Additionally, IκBζ suppresses Cxcl9, Cxcl10, and Ccl5 expression via HDAC3 and EZH2, which impairs the recruitment of NK and CD8+ T cells into the tumor, causing resistance to α-PD-1 immunotherapy in mice." (PMID 40562773, 2025). "Furthermore, HDAC3, as a part of the NCoR repressor complex, can suppress the expression of Cxcl10 and Ccl5 in several tumor entities, leading to T-cell and NK-cell exclusion from the TME and immunotherapy resistance." (PMID 40562773, 2025). "Conversely, in the presence of a systemic CXCL10 gradient, OS tumors that produce chemoattractants fail to recruit adequate immunity, compromising this potent immune-recruiting system and tipping the balance toward unchecked tumor growth and overt metastasis." (PMID 41516196, 2025). "Notably, consumption of the essential oil altered the profile of cytokines and chemokines, such as IFN-γ, IFN-α2, and CXCL10, in the tumor, and enhanced the cytotoxic activity of immune cells." (PMID 40429884, 2025). "These immune responses were accompanied by the increased production of inflammatory chemokines, such as CCL5, CXCL9, and CXCL10, which are critical for the recruitment of tumor-specific CD8+ T cells and functional DC and NK cells, which are associated with improved survival in NB patients." (PMID 40004078, 2025). "CXCL10 is a critical chemokine that attracts T cells into the tumor microenvironment." (PMID 40920775, 2025). "These contrasting roles highlight the context-dependent outcomes of JAK/STAT activation in CXCL10 signaling, which may be beneficial or detrimental depending on the tumor microenvironment, immune status, and co-activated pathways." (PMID 40760734, 2025).
tumor (continued). "Notably, two interferon-stimulated genes (ISGs) belonging to the CXCL chemokine family, Cxcl9 and Cxcl10, were the two most downregulated genes in the old tumor compartment." (PMID 41332581, 2025). "Regression was enhanced for CXCL10-secreting tumours, with three animals being tumour-free by day 22, then relapsing after day 26, as the CAR T cell BLI signal disappeared (median survival: 14 days, i.e. +27% compared with unmodified tumour-harbouring animals)." (PMID 41366257, 2025). "CXCL-9 and CXCL-10 are also known to be endogenous tumor angiogenesis inhibitors." (PMID 39996769, 2025). "Among the actions generated putatively through MDA5 are a further increase in Type 1 IFN, depression of MDSC, expansion of CD8 T cell populations through IL-15, CD8 targeting and infiltration of tumor through CXCL10, and a direct Type 1 IFN-dependent effect on tumor endothelium through VCAM-139." (PMID 38719809, 2024). "CXCL9-Fc and CXCL10-Fc significantly reduced tumor growth (day 13 P<0.05)." (PMID 39474427, 2024). "Additionally, exercise promotes the recruitment and activation of CD8+ T cells in tumors by driving Ccl5 and Cxcl10, thereby inducing anti-tumor immunity." (PMID 38622609, 2024). "CXCL10 is a chemokine that promotes anti-tumor activity by promoting T-cell infiltration of tumors." (PMID 38994949, 2024). "Given that Cxcl9 and Cxcl10 share the same receptor CXCR3, we hypothesized that Sin3B loss recruited CD8+ T cells into the tumor milieu predominantly through the CXCL9/10‐CXCR3 axis." (PMID 39316363, 2024). "Finally, we explored the mechanism by which exercise inhibited tumor progression by inducing EPI that promoting Ccl5 and Cxcl10 release from tumor cells further leading to enhanced T lymphocyte infiltration." (PMID 38622609, 2024). "It was observed that CXCL10 was significantly upregulated in tumor tissues (p = 0.003)." (PMID 38720149, 2024). "Il1α, Ccl2, Cxcl5, and Cxcl10 were significantly downregulated in Ifi35ko 4T1 tumor cells." (PMID 38216673, 2024). "Immunohistochemical analysis further revealed that microvessel density, as evidenced by the intensity of CD31 expression, was considerably decreased in Cxcl10-/- mice than in WT mice, event at an early stage (day 5) in which tumor sizes were comparable between WT and Cxcl10-/- mice." (PMID 39268223, 2024). "Finally, to further expand CXCL10-Fc therapy, it was administered three times, starting when tumor size reached vol of 50mm3." (PMID 39474427, 2024). "Notably, we found that neutralizing CXCL10 abolished the tumor-suppressive effects of Smad4 knockdown, indicating that CXCL10 inhibition by Smad4 was crucial for its oncogenic activity." (PMID 39346534, 2024). "CXCR3 expression remained markedly lower in the CX3CR1+ subset than in the CX3CR1− subset of Pmel-1 T cells in the spleen, suggesting that peripheral CX3CR1+ Pmel-1 T cells have a decreased capacity to migrate to the tumor microenvironment via the CXCR3-CXCL9/CXCL10 axis." (PMID 38881188, 2024). "EZH2-mediated DNA methylation associated with DNMT1 and H3K27me3 may inhibit the expression of the type 1 T helper cell (TH1) chemokines CXCL9 and CXCL10, as well as the subsequent transport of effector T cells to the tumor microenvironment." (PMID 38665224, 2024). "Recent studies have highlighted the importance of CD8a+ DCs and tumor-resident CD103+ DCs in antitumor immunity due to their ability to secrete chemokines such as CXCL10, which recruit T cells to the tumor, and cytokines such as IL-12 to enhance the type I inflammatory state of infiltrating T cells." (PMID 37917174, 2024). "We found that zebularine can induce CXCL10 expression in a variety of tumor cell lines." (PMID 38755254, 2024). "Due to the two-sided effect of CXCL10 in recruiting both cytotoxic cells and immunosuppressive cells, CXCL10 might have indicated heterogenous phenotypes of neutrophils in the cholestatic tumor microenvironment." (PMID 38951890, 2024).
tumor (continued). "As illustrated, tumor cell‐intrinsic Sin3B loss did not enhance the expression levels of Cxcl9 and Cxcl10 in either CAFs or macrophages within the TME." (PMID 39316363, 2024). "These three signatures consist of myeloid-focused cytokines (TNFa, GM-CSF, and IL-1b), chemokines (CCL3, CCL4, CCL5, CXCL9, and CXCL10), and an effector T-cell-derived cytokine (IFNg) and represent important aspects of a macrophage-based anti-tumor immune response." (PMID 39199551, 2024). "Therefore considering the key role CXCL10 plays in governing the recruitment of T cells into the tumor microenvironment, the use of alternative cell lines resulting in higher CXCL10 levels should and will be further explored in follow-up studies." (PMID 39220726, 2024). "Interestingly, IDI1 represses CCL5- and CXCL10-expressing cells in the tumor microenvironment, increasing the capacity for immune evasion." (PMID 38927057, 2024). "Likewise, the adoptive transfer of CXCR3+ CD8+ T cells into CXCR3KO mice enabled response to CXCL10-Fc, showing that the direct effect on CD8+ T cells induced by CXCL10-Fc is sufficient to restrain tumor growth." (PMID 39474427, 2024). "In conclusion, our study revealed that exercise could inhibit tumor onset and progression by promoting the release of adrenaline and harmonizing chemokines such as Ccl5 and Cxcl10." (PMID 38622609, 2024). "Additionally, research from Japanese scholars indicates that neutrophils expressing MHC class II and CXCL10 internally suggest a state of BCG-induced anti-tumor activity in BLCA." (PMID 38720149, 2024). "Indeed, the expression of CCL5, IFNG, CXCL9 and CXCL10 positively correlated among themselves as well as with the numbers of tumor-infiltrating NK cells in the original biopsy." (PMID 38167224, 2024). "Therefore, RT-mediated tumor therapies are considered for improving the anti-tumor efficacy of clinical immunotherapies by inducing tumor IFNα and CXCL10 expression." (PMID 38953994, 2024). "Activation of the cGAS/STING pathway and production of immunomodulatory molecules such as INF-α, IL-6, CXCL9 and CXCL10 were described to be involved in the enhanced migration of immune cells in cancer, particularly macrophages, and regulate anti-tumor immune response." (PMID 38587186, 2024). "CXCL10 has been demonstrated to coordinate anti-tumor immunity in BLCA." (PMID 38720149, 2024). "When immune checkpoint inhibitors are used in patients with high CXCL10 expression, they block inhibitory receptors on the surface of T cells, which triggers higher levels of immune cells to recognize and kill tumor cells, resulting in higher response rates and improved efficacy of cancer treatment." (PMID 38720149, 2024). "Furthermore, both the intrinsic antitumor properties of IRF1 and its ability to influence the formation of the tumor immune microenvironment through the IRF1/CXCL10/CXCR3 axis were demonstrated in hepatocellular carcinoma." (PMID 38396830, 2024). "Regarding changes in the mRNA expression of T cell-recruiting chemokine genes, a considerable increase was noted in Ccl3 expression in mouse tumor tissues after PT-100 or combination therapy, whereas Cxcl10 expression was substantially elevated in the PT-100, anti-PD-1 group, and combination groups." (PMID 38672409, 2024). "Our results indicated that IFNs mediated CXCL10 expression in tumor cells." (PMID 38953994, 2024). "CXCL10 may provide new therapeutic options to improve cancer treatment by targeting the tumor microenvironment in multiple cancers." (PMID 39443817, 2024). "This activation led to apoptosis in tumor cells through the CXCL10/CXCR3 paracrine axis." (PMID 38999981, 2024). "Whereas INFG and other cytokines, such as IL-6 and IL-10, did not exhibit any significant increase, this implies that the elevated levels of CXCL10 triggered by light may contribute to tumor regression." (PMID 39080467, 2024).
tumor (continued). "In addition, significantly improved therapeutic efficacy was also observed in the murine xenograft tumor models after combined therapy of radiotherapy and CXCL10 gene therapy." (PMID 39443817, 2024). "Its antitumor activity is associated with chemoattracting several types of immune cells, such as cytotoxic T lymphocytes, NK cells, NKT cells, and macrophages, which infiltrate a tumor and prevent its growth; CXCL10 promotes M1 polarization in inflammatory macrophages." (PMID 38891915, 2024). "In this study, higher levels of secreted CXCL10 in NCB patients may be reflective of pro-tumor activity due to overexpression of CXCR3 in the TME." (PMID 38236249, 2024). "Additionally, another key finding of this study was that ONB with high intra-tumoral CD8+ T cell infiltrates demonstrated significantly higher CXCL9 and CXCL10 tumor cell expression." (PMID 38822345, 2024). "The increase in IL-2 and CXCL10 might reflect the chemotaxis and enrichment of cytotoxic T cells at the tumor site and a better response to neoadjuvant chemoimmunotherapy." (PMID 38619623, 2024). "Therefore, we further investigate and demonstrate the detailed mechanism in this study by comparing the tumor-intrinsic IFNs and CXCL10 levels in the immunotherapy-sensitive CT26 and immunotherapy-resistant LL/2." (PMID 38953994, 2024). "Moreover, in these individuals, increased levels of CXCL9 and CXCL10 were linked to improved OS and a greater presence of CD8+ T cells within the tumor." (PMID 39273452, 2024). "Finally, comparative analysis between the spleen and tumor cells of mice treated with either CXCL10-Fc or control IgG showed that successful therapy led to a significant increase in CD4+ T cells and CD8+ T cells at the tumor site, but not spleen." (PMID 39474427, 2024). "Thus, although suppressive functions are generally attributed to TAMs, this specific role of CXCL9 and CXCL10 in anti-tumor immunity has suggested a potential use of TAMs to prevent T cell exhaustion and promote anti-PD-L1 responses." (PMID 39596815, 2024). "Moreover, it is essential for mediating the regulation of tumor cells in tertiary lymphoid organs (TLO) that immune cells (CXCL10+CD3+T) produce CXCL10." (PMID 38745115, 2024). "In summary, CXCL10+ M1 macrophages may promote the activation and differentiation of T cells to enhance anti-tumor immunity." (PMID 39170612, 2024). "Therefore, migration toward target cells is very important, and this process is regulated and guided by chemokines such as CXCL12, CXCL10, and CCL2, produced by tumor cells, tumor-associated macrophages, and fibroblasts." (PMID 39796680, 2024). "Cxcl10 and its receptor, Cxcr3, as well as granzyme A (Gzma) and granzyme B (Gzmb) levels, which support an activated T cell responses, were elevated in CR705Parp7KO tumours." (PMID 39867896, 2024). "Additionally, tumors with high CXCL10 expression correlated with increased infiltration of anti-tumor immune subsets, including CD4+ and CD8+ T cells and M1 macrophages, as well as elevated levels of the exhaustion markers CTLA4 and PD-1." (PMID 39409924, 2024). "Ki67 significantly increased in CD8+ and CD4+ T cells in both the spleen and the tumor site, indicating that CXCL10-Fc also induced these cells in the periphery, but the most significant result is at the tumor site where the relative tumor-specific CD8+ T cells are comparatively high." (PMID 39474427, 2024). "Migration of T cells into the tumor parenchyma may also involve chemotaxis in response to gradients of chemokines such as CXCL10." (PMID 38609390, 2024). "And macrophage-derived CXCL9 and CXCL10 are important for ICB-induced anti-tumor immunity." (PMID 38758367, 2024). "Overall, PD-L1 and CXCL10 levels in tumor tissues may be correlated according to the TCGA database in cBioPortal." (PMID 38953994, 2024).
tumor (continued). "The combined tumor mutational burden and immune-rich characteristics of CXCL10-high tumors make them attractive targets for ICI therapy and suggest that CXCL10 could serve as a potential biomarker for immunotherapy success in BCa." (PMID 39409924, 2024). "The EV-treated macrophages downregulated expression of M1 polarization-associated genes Cxcl9, Cxcl10 and Il12b, and had reduced capacity to attract activated T cells and to reactivate them to release IFN-γ, key components of an efficacious anti-tumor immune response." (PMID 38389103, 2024). "Furthermore, PDL1+ CXCL10+ macrophages are enriched in responding tumours, where they interact with the peripheral T cell compartment ensuring effective recruitment of primed effector-memory T cells into the TME." (PMID 38030622, 2023). "Interestingly, we also found that the Arf1‐ablated tumor cells induced a significant increase in the expression of Cxcl10 in the co‐cultured DCs." (PMID 37786300, 2023). "Th1 T cells may also amplify tumor immune defenses via the recruitment of cytotoxic leukocytes and the secretion of chemokines, including CXCL10 and CXCL9." (PMID 37766141, 2023). "In one trial, the upregulation of CXCL10 and interferon-α caused by such a vaccine promoted the trafficking of CD8+ T cells and CD68+ macrophages into the GBM site, thereby reducing active mitotic activity in the tumor." (PMID 38104126, 2023). "Various reports have addressed the source of CXCL10 in the tumor microenvironment." (PMID 37048082, 2023). "CXCL9 and CXCL10 also have the function of inhibiting endogenous tumor angiogenesis." (PMID 37046739, 2023). "CXCL10 is a chemokine that attracts T cells to tumor sites and is induced by IFNγ and Type I IFNs." (PMID 37404831, 2023). "CXCL10, encoding chemokines of the CXC subfamily and ligand for the receptor CXCR3, plays a role in some biological activities, which are relevant to various human diseases, such as dysfunction of immune and tumor development." (PMID 37198617, 2023). "Additionally, in an in vivo experiment using the same MC38 tumor xenograft model, the production of IFN-γ and CXCL10 in irradiated tumor tissue increased." (PMID 37048082, 2023). "In relation to CXCL10, we found it highly expressed in all the models analyzed; in agreement with that observation, similar results were obtained in tumoral tissue, where protein levels were higher at the tumor site than in the adjacent tissue." (PMID 37893029, 2023). "In addition, the mRNA expression of IFNB1, CCL5 and CXCL10 was markedly increased in TRIM21-KO tumours after IR treatment." (PMID 36797289, 2023). "Our present study provided valuable insights into the mechanism of thermal-ablation-based tumor immunotherapy and demonstrated that CXCL10 promoted CTLs to migrate into tumor tissues to enhance the synergistic anti-tumor effect of thermal ablation in combination with ICB." (PMID 36900218, 2023). "On the other hand, some chemokine signaling-related molecules (such as CXCL10 and CXCL11) were associated with better patient OS, and these chemokines secreted by pEMT-like tumor cells may promote the recruitment of IgG1 PCs via ACKR1." (PMID 37138324, 2023). "As the effect on tumor treatment may vary depending on the type or source of CXCL10 generation stimulation, specifying the stimulation and generation source is very important." (PMID 37048082, 2023). "Moreover, M-MDSCs can suppress tumor immunity via the CXCL10/TLR4/MMP14 signaling, thereby increasing tumor recurrence after liver transplantation." (PMID 36773210, 2023). "Gene expression analysis of the tumor lesions for selected immune-related genes, confirmed a clear induction of markers associated with T cell activation and recruitment in SD101-treated mice (Perforin, Icos, Cd38, Ifng, Il2ra, Il7 and Cxcl10)." (PMID 37365634, 2023). "Additionally, autophagy inhibition enhances chemokine secretion (CCL5 and CXCL10) into the tumor bed." (PMID 38071322, 2023).